ATF3 (activating transcription factor 3)
Diseases named in the same sentence as ATF3 in open-access papers (continued):
Sharing a sentence is not in itself a finding about the gene and the disease.
fibromyalgia (1 paper, 2025). A chronic disorder of unknown etiology characterized by pain, stiffness, and tenderness in the muscles of neck, shoulders, back, hips, arms, and legs. "In addition, a study using a repeated cold stress protocol as a fibromyalgia model showed that activation of proprioceptors induced sustained pain and spinal microglial reactivity, although this model also upregulated ATF3 expression in proprioceptors, suggesting additional mechanisms." (PMID 40705704, 2025).
glaucoma (1 paper, 2025). Increased pressure in the eyeball due to obstruction of the outflow of aqueous humor. "More patients with different types of glaucoma and glaucoma at different stages should be included in future studies, in order to further explore the potential of ATF3 as a clinical marker of glaucoma." (PMID 41181154, 2025). "This study revealed significant up-regulation of ATF3 expression in peripheral blood serum samples from patients with glaucoma." (PMID 41181154, 2025). "In addition, peripheral venous blood samples and aqueous humor were collected from 20 individuals, 10 patients with primary angle-closure glaucoma and 10 controls, to detect changes in ATF3 expression." (PMID 41181154, 2025). "Therefore, understanding the changes in ATF3 expression in the aqueous humor or serum of RIR mice and the blood of patients with different degrees of glaucoma will reveal whether ATF3 can be employed as a clinical diagnostic or prognostic marker for optic neurodegenerative diseases." (PMID 41181154, 2025).
glomerular disease (1 paper, 2018). "ATF3 was low in normal glomeruli from patients without glomerular disease." (PMID 29038896, 2018). "We found low-level ATF3 protein in individuals without glomerular disease; in contrast, patients with MCD, FSGS, or DN had a significant increase in ATF3 protein, and an even stronger ATF3 expression was found in glomeruli cells from DN patients." (PMID 29038896, 2018).
glomerulosclerosis (1 paper, 2018). A hardening of the kidney glomerulus caused by scarring of the blood vessels. "Because NFAT signaling mediates regulation of factors important for podocyte function and glomerulosclerosis, we explored whether ATF3 has a direct role in regulating NFATc1 gene promoter activity." (PMID 29038896, 2018).
gram-negative bacterial infections (1 paper, 2022). Infections caused by bacteria that show up as pink (negative) when treated by the gram-staining method. "In the case of Gram-negative bacterial infection, ATF3 acted as a negative regulator to inhibit the production of inflammatory cytokines during the invasion of Escherichia coli and Neisseria gonorrhoeae." (PMID 35370996, 2022).
H1N1 influenza (1 paper, 2023). "Atf3CreERT2; ROSA26LSL-tdTomato (Atf3-tdTm) adult mice (5–13 weeks old) received 200 mg/kg tamoxifen by oral gavage 8 days after H1N1 influenza injury (8 dpi) and were treated with EdU ad libitum in their drinking water from 8 to 14 dpi." (PMID 37233732, 2023).
haemorrhagic stroke (1 paper, 2024). "Furthermore, it would be intriguing to explore whether human serum ATF3 could also serve as a biomarker for other CNS injuries, such as TBI or haemorrhagic stroke, in future investigations." (PMID 38649772, 2024).
hemophilia (1 paper, 2023). Hemophilia is a genetic disorder characterized by spontaneous hemorrhage or prolonged bleeding due to factor VIII or IX deficiency. "Since inhibitor development in hemophilia depends on Tfh cells and a productive germinal center response, this link between Atf3 and Tfh cell survival should be further explored." (PMID 37954612, 2023).
hyperlipidemia (1 paper, 2022).
hypertrophic cardiomyopathy (1 paper, 2025). A condition in which the myocardium is hypertrophied without an obvious cause. "The hearts of Tg(myl7:ATF3) zebrafish displayed a more compact and thickened ventricular wall compared to control WT zebrafish, resembling phenotypes associated with hypertrophic cardiomyopathy (HCM)." (PMID 41453996, 2025).
Hypoglycemia (1 paper, 2013). A decreased concentration of glucose in the blood. "Hypoglycemia caused increased expression of CHOP and ATF3, and this increase was effectively blocked by 100 nM VCD, similar to what was observed in the case of GRP78." (PMID 23755268, 2013). "The lack of increased GRP78 (and CHOP and ATF3) levels under dual (hypoglycemia plus hypoxia) treatment condition precluded the intended addition of VCD to this condition." (PMID 23755268, 2013). "In the case of ATF3, we focused on earlier time points because stimulation of this general stress marker takes place more rapidly as compared to GRP78 or CHOP, and greatly elevated levels were present as early as 2.5 hours (hypoxia) and 7.5 hours (hypoglycemia)." (PMID 23755268, 2013).
imbalance (1 paper, 2021). "Thence, as one of the main regulators of metabolic homeostasis, ATF3 may be a valuable target for precise treatment of metabolic imbalance, immune disorders and cancer." (PMID 34790227, 2021).
Impaired glucose tolerance (1 paper, 2014). An abnormal resistance to glucose, i.e., a reduction in the ability to maintain glucose levels in the blood stream within normal limits following oral or intravenous administration of glucose. "In vivo Atf3-silencing reversed ethanol-mediated Gck down-regulation and β-cell dysfunction, followed by the amelioration of impaired glucose tolerance and insulin resistance." (PMID 25074928, 2014). "As expected, the impaired glucose tolerance (GTT and OGTT) and insulin tolerance (ITT) induced by ethanol consumption were markedly inhibited by the administration of Atf3 siRNA." (PMID 25074928, 2014).
Infertility (1 paper, 2021). "We, therefore, wondered whether an element of the infertility phenotype could be caused by an alteration in the expression of ATF3." (PMID 33846304, 2021).
interstitial lung disease (1 paper, 2021). A diverse group of lung diseases that affect the lung parenchyma. "In non-oncological diseases, Wu once reported that pirfenidone could inhibit fibroblast-to-myofibroblast transition via downregulation of ATF3 in RA-associated interstitial lung disease." (PMID 34966780, 2021).
intestinal infection (1 paper, 2018). "Indeed, we found that ATF3−/− mice were more susceptible to intestinal infection by Citrobacter rodentium." (PMID 30455690, 2018).
ischemic heart disease (1 paper, 2024). "Notably, ATF3 plays an important and complicated role in ischemic heart disease as a protector or facilitator." (PMID 39195894, 2024). "Finally, we showed a negative association of GAS6 and ATF3 expression with the risk of major adverse cardiac events in patients with ischemic heart disease." (PMID 39195894, 2024).
joint disease (1 paper, 2018). "The involvement of ATF3 in joint disease has not been well studied, the ATF3 gene which belongs to the ATF/cAMP-responsive element-binding protein family and encodes a member of the activating transcription factor." (PMID 30186872, 2018).
keratoconus (1 paper, 2020). A degenerative, structural disorder of the eye, characterized by a cone-shaped protrusion of the cornea. "The gene encoding cyclic AMP dependent transcription factor ATF3, decreased in both groups, regulates cell proliferation and differentiation, and is a stress response gene that interacts with JUN and FOS; additionally, related genes, JUND and FOLSL1 are both downregulated in the keratoconus samples." (PMID 32555404, 2020).
kidney cancer (1 paper, 2021). Primary or metastatic malignant neoplasm involving the kidney. "Furthermore, the findings suggest that ATF3 may be a potential biomarker for kidney cancer diagnosis and prognosis." (PMID 33816467, 2021).
leishmaniasis (1 paper, 2019). Infectious disease that is transmitted through the bite of hematophagous female phlebotomine sand flies. "Finally, it is likely that in the present experimental condition, leishmaniasis induces an inflammatory pain since there was no detection of altered ATF3 mRNA expression in DRG neurons." (PMID 31138231, 2019).
lentivirus infection (1 paper, 2025). Virus diseases caused by the Lentivirus genus. "Given that the vector’s promoter is inducible by doxycycline, we introduced doxycycline 24 h after lentivirus infection to induce stable ATF3-knockdown (ATF3-kd) cell lines." (PMID 39996726, 2025).
leptospirosis (1 paper, 2022). A contagious bacterial infection caused by spirochetes of the genus Leptospira. "Activating transcription factor 3 (ATF3), a transcriptional factor involved in either anti-apoptosis or anti-inflammation process during systemic infection may be an interesting molecule in terms of leptospirosis with AKI." (PMID 35203344, 2022).
liver dysfunction (1 paper, 2025). "Studies using the TTR-ATF3 vector for Atf3 overexpression, for example, report repressed gluconeogenesis and symptoms of liver dysfunction in transgenic mice." (PMID 40158856, 2025).
long QT syndrome (1 paper, 2025). "Electrocardiogram measurements indicated that ATF3 overexpression induced symptoms resembling long QT syndrome, suggesting electrical dysfunction." (PMID 41453996, 2025).
lupus (1 paper, 2022). "The inability of lupus HDL to suppress inflammatory responses is due to a reduced capacity to stimulate ATF3 production and nuclear translocation, which is triggered by oxidized LDL receptor signaling." (PMID 35282557, 2022). "Indeed, systemic administration of an HDL mimic to lupus-prone animals resulted in considerable ATF3 activation and reductions in proinflammatory cytokine levels, indicating therapeutic potential." (PMID 35282557, 2022).
lymphoblastic leukemia (1 paper, 2020). "MYC, CXCL8, and ATF3 were considered the hub genes and queried on Oncomine database and cBio portal platform to investigate their gene expression and genetic alterations in lymphoblastic leukemia." (PMID 32096603, 2020).
memory impairment (1 paper, 2022). "The expression level of ATF3 mRNA was shown to be highly elevated in the CA1 region of the hippocampus of CCI patients with memory impairment, and it has also been linked to the pathological process of pain." (PMID 35547819, 2022). "However, it is unknown if ATF3 overproduction in the CA1 region of the hippocampus is related to memory impairment caused by CCI and the mechanism." (PMID 35547819, 2022). "ATF3 was highly increased in the hippocampus DEGs of CCI-induced memory impairment rats compared to the sham group, according to our RNA-Seq profiles." (PMID 35547819, 2022). "As a result, 3 DEmRNAs from CCI with memory impairment model rats (ATF3, C1QC, and CD68) and 13 DEmRNAs from SNI and CCI models (ADAMTS2, BCL6B, CLCF1, RBP1, and TPBG, among others) overlapped with SNI and CCI models, respectively." (PMID 35547819, 2022). "We also used western blot to confirm ATF3 expression and discovered that the level of ATF3 expression in the hippocampus CA1 area of CCI with memory impairment model rats 21 days is considerably higher." (PMID 35547819, 2022). "We also discovered that ATF3 was considerably overexpressed in the hippocampal CA1 area, and gene markers of ferroptosis, such as GPX4, SLC7A11, SLC1A5, and PTGS2, were dysregulated in the CCI-induced memory impairment paradigm." (PMID 35547819, 2022).
meningioma (1 paper, 2022). A generally slow growing tumor attached to the dura mater. "Moreover, our Ingenuity Pathway Analysis revealed that the transcription factors ATF3, ATF4, ATF6, and XBP1 were activated in meningioma cells exposed to DSF/Cu." (PMID 35453636, 2022).
myoma (1 paper, 2022). "Interestingly, the 2.9-fold increase in ATF3 protein expression in western blot analysis is important evidence that myoma-related mechanical stress may play a role in the up- and/or downregulation of genes in the endometrium and myometrium." (PMID 36430682, 2022).
myopia (1 paper, 2026). "ATF3, GRIN2B, and GSTM3 have emerged as promising oxidative stress-related biomarkers with significant potential for understanding myopia pathology." (PMID 41912634, 2026).
nutritional disease (1 paper, 2024). "The top-scoring network for the 9h-DEGs, also consisting of ATF3, ATF6, and DDIT3, was associated with cell-to-cell signaling and interaction, nutritional disease, and organismal injury and abnormalities (score = 41)." (PMID 39466820, 2024).
parasitic infection (1 paper, 2020). "We found that the FBAHs detached from the Atf3 overexpressing adipose tissue 48 hr after parasitic infection, and lamellocyte differentiation and capsule formation was not impaired to a noticeable extent when compared to control larvae." (PMID 33026342, 2020).
Parkinson disease (1 paper, 2021). A progressive degenerative disorder of the central nervous system characterized by loss of dopamine producing neurons in the substantia nigra and the presence of Lewy bodies in the substantia nigra and locus coeruleus. "Our lab has established a role for activating transcription factor 3 (ATF3) and Parkinson Disease (Autosomal Recessive, Early Onset) 7 or DJ-1 in the regulation of Nrf2." (PMID 33246293, 2021).
periodontal diseases (1 paper, 2025). "To investigate the relationship between periodontal disease and ATF3 expression, we analyzed data from the NCBI GEO database." (PMID 40430099, 2025).
Pneumocystis infection (1 paper, 2021). "In our study, Pneumocystis infection caused the elevated proportion of a subcluster of naïve B cells, with the high expression of the ATF3 gene." (PMID 34135870, 2021).
posttraumatic stress disorder (1 paper, 2018). "The enhanced freezing behavior and normal spatial memory of the Atf3 knockout mice resembles the fear response and numbing symptoms often exhibited by patients affected with posttraumatic stress disorder." (PMID 29515366, 2018).
prosaposin deficiency (1 paper, 2008). "Atf3 and Nfia could be potential candidates that regulate disease progression in prosaposin deficiency at later ages." (PMID 18673548, 2008).
Pruritus (1 paper, 2023). Pruritus is an itch or a sensation that makes a person want to scratch. "Second, while our data strongly support the involvement of peptidergic neurons (IL-31RA+TRPV1+) in CTCL-associated pruritus, we do not exclude the role of nonpeptidergic neurons in which ATF3+ is expressed." (PMID 36520531, 2023).
Pseudomonas infection (1 paper, 2016). Infections with bacteria of the genus pseudomonas. "In our study, early at 2 hrs after Pseudomonas infection, a lowering of ncRNAs preceded the up-regulation of the stress-activated transcription factors, ATF3 and ATF6, and the down-regulation of skin-enriched genes at 6 and 24 hrs." (PMID 27792773, 2016).
psoriasis (1 paper, 2017). An autoimmune condition characterized by red, well-delineated plaques with silvery scales that are usually on the extensor surfaces and scalp. "ATF3 is reported as transcription factor involved in the pathogenesis of epithelial cancer and psoriasis." (PMID 28982115, 2017).
pulmonary diseases (1 paper, 2023). "However, the role of ATF3 in current studies is controversial, and there are reports showing that ATF3 plays different roles in different pulmonary diseases." (PMID 37773692, 2023).
pulpitis (1 paper, 2025). Inflammation of the dental pulp. "An experimental pulpitis mouse model was established, and HE staining revealed that ATF3 overexpression reduced the area of pulp necrosis." (PMID 39801194, 2025). "The aim of this study is to investigate the expression and regulatory mechanisms of ATF3, a potential therapeutic marker, in pulpitis." (PMID 39801194, 2025). "A mouse pulpitis model with different degrees of inflammation is established, and the expression of ATF3 in pulpitis is explored." (PMID 39801194, 2025). "Moreover, we found that ATF3-positive cells were abundantly expressed in normal pulp tissues, and the more severe the inflammation in pulpitis was, the lower the number of ATF3-positive cells." (PMID 39801194, 2025). "In the present study, we found for the first time that the activating transcription factor ATF3 was aberrantly expressed in pulpitis and that the ATF3/WNT4 axis promoted the osteogenic differentiation of pulp stem cells by modulating the polarization and inflammatory response of M2 macrophages." (PMID 39801194, 2025). "To investigate whether ATF3 promotes macrophage migration in pulpitis, we performed IHC analysis of the M1 macrophage marker CD86 and the M2 macrophage marker CD206." (PMID 39801194, 2025). "Our findings suggested that ATF3 is a potential target for pulpitis treatment." (PMID 39801194, 2025). "To investigate whether ATF3 has the same mechanism of action in pulpitis, we first explored the expression pattern of ATF3 in pulpitis." (PMID 39801194, 2025). "Therefore, we speculated that ATF3 might be involved in the progression of pulpitis, and surprisingly, we detected low expression of ATF3 in both experimental pulpitis models and human pulpitis samples." (PMID 39801194, 2025). "Therefore, we hypothesized that ATF3 positively regulates WNT4 and inhibits the progression of pulpitis." (PMID 39801194, 2025).
retinal tumor (1 paper, 2014). "While atf3 was dramatically increased in expression in the Tg(flk1:RFP)is18 retinal tumors, zebrafish bystin-like (bysl) showed no change in expression level." (PMID 25485542, 2014).
serous ovarian cancer (1 paper, 2015). "Lysophosphatidic acids triggers the expression of both miR-30c-2-3p and ATF3, which peak at 1 h and are absent 8 h post stimulation in SKOV-3 and OVCAR-3 serous ovarian cancer cells." (PMID 26418018, 2015).
silicosis (1 paper, 2026). Silicosis is a respiratory disease caused by breathing in (inhaling) silica dust. "Single-cell RNA sequencing (scRNA-seq) of healthy and silicosis human and mouse lung tissues revealed that activating transcription factor 3 (ATF3)-mediated macrophage senescence is closely linked to silicosis progression." (PMID 42160006, 2026). "Collectively, our study provided insights into the mechanism by which deacetylated ATF3 facilitates silicosis progression via increased nuclear transport and macrophage senescence, and indicated potential therapeutic targets for PF." (PMID 42160006, 2026).
Sjögren’s syndrome (1 paper, 2025). "In the realm of natural compounds, recent studies have revealed that apigenin modulates Sjögren’s syndrome-induced ferroptosis in salivary gland epithelial cells through the ERα signaling-mediated ATF3/SLC7A11 axis." (PMID 40934008, 2025).
somatotroph adenoma (1 paper, 2017). "In summary, we revealed that metformin inhibited somatotroph adenoma cell growth through an ATF-3-mediated pro-apoptotic effect both in vitro and in vivo." (PMID 28380462, 2017).
staphylococcal infection (1 paper, 2022). An infection caused by Staphylococcus. "In conclusion, our data suggest that ATF3 promotes the inflammatory response of macrophages in the early stages of staphylococcal infection regardness of lung released pro inflammatory cytokines." (PMID 35370996, 2022). "Given the importance of macrophages in host defense against bacterial infections, we next evaluated the effect of ATF3 on macrophages during staphylococcal infection." (PMID 35370996, 2022).
stress ulcers (1 paper, 2021). "Additionally, an ATF3 deficiency exacerbated the leakage in mice, suggesting that ATF3 plays a protective role in stress ulcers." (PMID 34944038, 2021). "ATF3 deficiency greatly exacerbates stress-induced GI damages, suggesting a protective role of ATF3 toward the stress ulcer." (PMID 34944038, 2021). "The role of ATF3 in stress ulcers, however, remains elusive." (PMID 34944038, 2021). "Therefore, observing the GI epithelial cell protective effects of ATF3 in stress ulcers is reasonable." (PMID 34944038, 2021). "However, the role of ATF3 in GI cellular stress and injury in acute stress ulcers is less discussed." (PMID 34944038, 2021).